EGFR (epidermal growth factor receptor)
Diseases named in the same sentence as EGFR in open-access papers (continued):
Sharing a sentence is not in itself a finding about the gene and the disease.
glioblastoma (continued). "In the cell death pathway, EGF treatment induces apoptosis via AKT1 inhibition in EGFR overexpressed dominant-negative Ras mutant cell lines, or via phosphorylation of STAT3 in glioblastoma; however, the mechanisms for these pathways are not clear." (PMID 38789573, 2024). "Only three patients who had both EGFR and TERT data did not have the molecular characteristics of glioblastoma." (PMID 38672254, 2024). "Previous study found that verteporfin preferentially induced apoptosis of cultured patient‐derived EGFR‐amplified/mutant Glioblastoma (GBM) cells, suppressed expression of YAP/TAZ transcriptional targets and conferred significant survival benefit in an orthotopic xenograft GBM model." (PMID 38468490, 2024). "As a result, clinical trials in EGFR-amplified patients of anti-EGFR therapies have been performed (INTELLANCE1—NCT02573324, INTELLANCE2—NCT02343406) but have not yet shown sustained clinical benefit in primary glioblastoma." (PMID 36765632, 2023). "In this study, we performed integrated epigenome-wide DNA-methylation profiling of 866,895 methylation specific sites in 50 glioblastoma IDH wildtype samples, comparing EGFR amplified and non-amplified glioblastomas." (PMID 37444635, 2023). "EGFR, Integrin αvβ3, Neuropilin-2, and PDGFRα, but not CD90 and CD147, were significantly upregulated in glioblastoma than normal brain tissues by GEPIA analysis." (PMID 37146061, 2023). "We further confirmed the cytotoxic potential of our lead combination involving EGFR/ERBB2 inhibitor (lapatinib) with DDR1/BCR-ABL inhibitor (nilotinib) in radioresistant spheroids of HCT116 (COAD) and, in an additional devastating primary cancer model, glioblastoma (GBM)." (PMID 35664781, 2022). "PriGO8A cells were isolated from a glioblastoma patient under conditions that preserve neural stem cell–like characteristics and are PTEN-null, C250T TERT promoter mutant, and without EGFR amplification." (PMID 34624316, 2021). "EGFR, which is known to be upregulated in infiltrating gliomas, showed very low expression in LMS4, unlike other tested glioblastomas, and moderate overexpression in DIS6, without phosphorylation." (PMID 33853673, 2021). "Additionally, epidermal growth factor receptor (EGFR) gene amplification could not be identified in CD34+ endothelial cells within the vascular linings of glioblastoma tissue, further supporting the unlikely contribution of glioblastoma cells to tumor vessel formation." (PMID 32375250, 2020). "Mutations identified in the radiation-associated DIPGs had significant molecular overlap with recurrent drivers of adult glioblastoma (e.g. NRAS, EGFR, and PTEN), as opposed to epigenetic dysregulation in H3-driven primary DIPGs." (PMID 30049282, 2018). "It is important to note that the nonclassical glioblastomas (mesenchymal, proneural, and neural subtypes) frequently display NFKBIA (NF-kB Inhibitor-α, a modulator of NF-kB and EGFR signaling) gene deletions." (PMID 30279357, 2018). "Unlike the ATP-competitive TKIs, PTUPB treatment does not deplete EGF-induced phosphorylation of EGFR (p-EGFRTyr1173) until 6 h post dose, while Gefitinib, a widely-used EGFR TKI, inhibits EGF-induced p-EGFR in early phase (30 min) in glioblastoma cells." (PMID 29152086, 2017). "It is possible that RT treatment does not activate the EGFR pathway in canine OSA cells as it occurs with human carcinoma and glioblastoma cells." (PMID 27245053, 2016).
glioblastoma (continued). "In U87 glioblastoma cells, ouabain did not inhibit EGF-induced Erk1/2 or Akt activation and, surprisingly, further increased EGF-induced EGFR phosphorylation." (PMID 25052069, 2014). "Orthotopic xenograft animal model from human glioblastoma multiforme (GBM) cell lines often do not recapitulate an extremely important aspect of invasive growth and epidermal growth factor receptor (EGFR) gene overexpression of human GBM." (PMID 21314332, 2011). "Preclinical studies suggested synergistic effects upon combined EGFR and mTOR pathway inhibition in non-SCLC and breast, squamous cell carcinoma, glioblastoma, colon, pancreatic cancer and biliary tract cancer." (PMID 20683448, 2010). "Notably, IL-6 and the IL-6 signaling cascade support glioblastoma tumorigenesis and stemness, and we identified that genes involved in the IL-6 signaling pathway, such as ANXA1, LGALS3, and EGFR, were enriched in ICI non-responders pre-ICI 28–30." (PMID 40161763, 2025). "Notably, there was an absence of focal EGFR amplification in the de novo RRD glioblastomas (0/9, 0%), which was present in 45% (203/450) of the conventional glioblastomas." (PMID 38079020, 2023). "No tumors demonstrated EGFR amplification, MET amplification, CDK4 amplification, MDM2 or MDM4 amplification, PTEN homozygous deletion, or NF1 homozygous deletion that are frequent oncogenic events in conventional IDH-wildtype glioblastomas." (PMID 38079020, 2023). "However, LANCL2 or EGFR amplification, and their co-amplification had no significant impact on OS in older (≥ 60 years) or IDH1/2-wild-type glioblastoma patients." (PMID 34461927, 2021). "However, these tumors had few IDH-wildtype glioblastoma-like SCNA features: none had + 7/ − 10 and only one displayed EGFR amplification." (PMID 34863298, 2021). "However, mRNA or protein expression of EGFR and LANCL2 was not significantly correlated with OS of glioblastoma patients." (PMID 34461927, 2021). "However, inhibiting PLCγ disrupts the invasion of glioblastoma cells into normal brain tissues, regardless of the combined signaling effects of PDGFR, NGF, IGF-1, and EGFR upregulation." (PMID 32276377, 2020). "Furthermore, mutations, overexpression or downregulation of PTEN (phosphatase and tensin homolog on chromosome 10) or EGFR (epidermal growth factor (EGF) receptor), both common in glioblastomas, are possible modulators of Akt activation or negative regulation." (PMID 30709059, 2019). "While EGFR reportedly induces ANGPTL4 expression and promotes tumor angiogenesis in malignant gliomas, ANGPTL4 activation apparently is independent of EGFR upregulation in Mesenchymal glioblastoma xenografts." (PMID 25955030, 2015). "In glioblastomas (data not shown), PFS was significantly better for patients with no EGFR amplification (5.4 vs. 8.4 months, p=0.01), no expression of EGFRvIII mutant mRNA (3.7 vs. 8.4 months, p=0.04), or weak EGFRv2 (3.3 vs. 5.6 months, p=0.04) or -v4 mRNA levels (8.4 vs. 4.7 months, p=0.05)." (PMID 22159595, 2012). "Using the same signature, we found the TGFβ strong response cluster overlapped with the weak autocrine PGDG signaling subgroup extensively (data not shown), suggesting potential collaboration between EGFR/PTEN/PI-3K pathway and TGFβ pathway in glioblastoma development and progression." (PMID 19192267, 2009). "The other glioblastoma had a similar expression level difference between wild-type and EGFRvIII transcripts (Ct value difference of ∼1.5) as the three glioblastomas that had not been detected by PAC, but had lower overall EGFR transcript levels." (PMID 18688287, 2007).
glioblastoma (continued). "Specifically, we analyzed EIF4EBP1 mRNA expression levels in EGFR-amplified and EGFR-non-amplified as well as in O6-methylguanine DNA methyltransferase (MGMT) promoter-methylated and promoter-unmethylated IDH-wildtype glioblastoma patient samples using publically available datasets." (PMID 35228525, 2022). "In glioma cells, increases in EGFR protein levels correlated with elevated activity of PKC and mTORC1, and signals from EGFR to mTORC1 were through PKCα and independent of AKT, while in glioblastoma cells, PKCη was involved in mTOR activation and proliferation." (PMID 28926616, 2017).
colorectal cancer (2,204 papers, 1992 to 2026). A primary or metastatic malignant neoplasm that affects the colon or rectum. "Presently, BRAF and KRAS mutations are significant biomarkers in colorectal cancer classification, primarily because they are reliable predictors of treatment response and prognosis, particularly for anti-EGFR therapy." (PMID 40722718, 2025). "KRAS mutations are common in colorectal cancer (30%–50%) and are considered important molecular markers for predicting the efficacy of the anti-EGFR monoclonal antibodies, cetuximab, and panitumumab." (PMID 40421293, 2025). "On the other hand, microsatellite stable BRAF mutant colorectal cancers are particularly aggressive, yet the mutation also increases responsiveness to EGFR inhibitor therapy." (PMID 41310156, 2025). "Among the various effects of OMT-110, its efficacy in human colorectal cancer with epidermal growth factor receptor (EGFR) mutations and sufficient safety margins in terms of dosage have been previously confirmed." (PMID 40414889, 2025). "In advanced colorectal cancer, these mechanisms cause a decrease in the effectiveness of EGFR inhibitors." (PMID 40142219, 2025). "PIK3CA mutations occur in about 15%–20% of colorectal cancer cases and are often associated with resistance to some types of chemotherapy and anti-EGFR therapy." (PMID 40083375, 2025). "For initial treatment of advanced BRAF-mutated colorectal cancer, combining doublet chemotherapy with anti-EGFR/BRAF therapy offers the best survival benefit." (PMID 41355781, 2025). "This disparity stems from their distinct mechanisms of action: EGFR antibodies effectively target EGFR overexpression regardless of mutational status, a characteristic feature of colorectal cancers." (PMID 40058234, 2025). "It has been reported that the upstream activation of several RTKs interferes with the KRASG12C blockade, and EGFR signaling appears to be a predominant mechanism underlying colorectal cancer resistance to AMG510." (PMID 40076615, 2025). "The approval of anti-EGFR/BRAF regimens for second line treatment of BRAF-mutated colorectal cancer underscores its clinical significance." (PMID 41355781, 2025). "Experiment in vivo confirmed that EGFR signaling in myeloid cells represents the main player of colitis-associated colorectal cancer (CAC), by activation of STAT3 and survivin genes in intestinal tumor cells." (PMID 39966897, 2025). "Collectively, our study found that dual target inhibition of EGFR/BRAF drives the core antitumor activity in BRAF-mutated colorectal cancers." (PMID 41355781, 2025). "A secondary mutation in the ectodomain of the EGFR, specifically S492R, conferred resistance to cetuximab in colorectal cancer by obstructing the binding of the EGFR antibody to its target." (PMID 40342734, 2025). "Using multiple meta-analysis approaches, we found that anti-EGFR/BRAF based regimens represent an optimal therapeutic strategy for patients with advanced BRAF-mutated colorectal cancer." (PMID 41355781, 2025). "In conclusion, our study demonstrates that cetuximab-IRDye800CW enables stable, tumor-specific, and high-contrast fluorescence imaging in colorectal cancer models, with performance closely linked to EGFR expression." (PMID 41346398, 2025). "Elevated miR-31-3p levels have also been linked to resistance to anti-EGFR therapies in colorectal cancer, potentially through the regulation of downstream signaling pathways such as RAS/RAF/MEK/ERK, which can bypass EGFR inhibition." (PMID 41002715, 2025). "Elevated AREG expression is commonly observed in colorectal cancer and has been associated with poorer prognosis and resistance to anti-EGFR monoclonal antibodies such as cetuximab and panitumumab." (PMID 41515404, 2025). "Mutations in these genes, especially BRAFV600E, are associated with resistance to anti-EGFR agents and can impact overall survival, especially in specific subtypes of colorectal cancer." (PMID 40722718, 2025).
colorectal cancer (continued). "In BRAF V600E-mutated colorectal cancer, the combination of encorafenib, binimetinib, and the EGFR inhibitor cetuximab has shown significant clinical activity, leading to FDA approval of this treatment regimen." (PMID 40688855, 2025). "The role of PIK3CA mutation and PTEN status in mediating EGFR‐directed therapy resistance in colorectal cancer is still unclear." (PMID 40302146, 2025). "Epidermal growth factor receptor (EGFR) is overexpressed in colorectal cancer and associated with aggressive tumour biology and poor prognosis." (PMID 39859271, 2025). "Our findings established the anti-EGFR/BRAF based regimen as optimal strategy for patients with BRAF-mutated colorectal cancer in both first line and second line settings." (PMID 41355781, 2025). "Aberrant activation of EGFR signaling is frequently associated with pathological conditions such as colorectal carcinoma, where it contributes significantly to tumor development and metastasis." (PMID 39941081, 2025). "KRAS and BRAF mutations are important biomarkers in the management of colorectal cancer as they are not only predictive of response to anti-EGFR therapy but are also of prognostic value." (PMID 39364024, 2024). "AREG, an epidermal growth factor receptor (EGFR) ligand, is upregulated in colorectal cancer (CRC) tissue and is associated with tumor invasion depth, nerve infiltration, and liver metastasis." (PMID 39683442, 2024). "Dual targeting of B7-H3 and EGFR markedly rescued the susceptibility to chemotherapy in colorectal cancer cells in vitro and in vivo." (PMID 38370387, 2024). "KRAS mutations, present in approximately 40% of colorectal cancers, are associated with resistance to EGFR inhibitors, complicating treatment." (PMID 39221315, 2024). "EGFR is overexpressed in about 80% of colorectal cancers and is associated with poor prognosis and resistance to chemotherapy." (PMID 39417449, 2024). "Acquisition of resistance to cetuximab, an antibody-based EGFR inhibitor, is associated with an increase in EphB3 expression levels and EphB3/EGFR binding in colorectal cancer cells." (PMID 38391938, 2024). "Combination therapies with allele‐specific covalent KRAS p.G12C inhibitors and anti‐EGFR targeted therapy have recently shown promising results in advanced colorectal cancer patients with KRAS c.34G>T (p.G12C) mutation." (PMID 39039804, 2024). "Although loss of function mutations in RNF43 are currently not directly targetable, they have been associated with the response to anti-EGFR/BRAF combination therapies in microsatellite-stable BRAF-mutated colorectal cancers." (PMID 39452477, 2024). "In colorectal cancer, mutations in downstream molecules of EGFR, such as KRAS, NRAS or PI3K, can lead to a loss of response to anti-tumor drugs targeting EGFR and result in a poor prognosis for patients." (PMID 39000374, 2024). "In lung and colorectal cancer patients who have acquired resistance to EGFR inhibitors, class I BRAF mutations are often detected." (PMID 39529955, 2024). "All these kinases displayed mutations in more than 6% of CDX2-suppressed colorectal cancers in the TCGA cohort, and some receptor tyrosine kinases, including EGFR, ERBB3, ERBB4, RET, ROS1, and ALK, showed even higher mutation rates in these cancers." (PMID 39452477, 2024). "EGFR overexpression is observed in a significant subset of colorectal cancers and elevated EGFR signaling is associated with enhanced tumor growth and metastasis." (PMID 39130636, 2024). "Among these factors, the signaling pathway involving EGFR is directly linked to the oncogenesis and progression of colorectal cancers." (PMID 38892434, 2024). "We think that a standard scoring system should be adopted for a more objective evaluation of the association between EGFR status and prognostic markers and to decide the optimal targeted therapy option in patients with colorectal cancer." (PMID 38650801, 2024).